STX3 (syntaxin 3)
Description:
Potentially involved in docking of synaptic vesicles at presynaptic active zones. Apical receptor involved in membrane fusion of apical vesicles. [Isoform B]: Essential for survival of retinal photoreceetors. [Isoform 3]: Functions as a regulator of gene expression.
Synonyms: STX3A; DIAR12; MVID2; RDMVID
Tractability: Antibody: UniProt places it where antibodies can reach, with high confidence; its Gene Ontology location is reachable by antibodies, with high confidence; UniProt predicts a signal peptide or a membrane-spanning region. PROTAC: ubiquitination databases record sites on it; its protein half-life has been measured.
Gene: Protein-coding gene on chromosome 11 (59,713,456 to 59,805,882, forward strand). Ensembl gene ENSG00000166900.
Subcellular location: Apical cell membrane (Isoform A); Nucleus (Isoform 3)
Subcellular location (Human Protein Atlas): Vesicles; Nuclear membrane
Pathways (Reactome):
Immune System: Other interleukin signaling
Gene Ontology:
Molecular function: protein binding; arachidonate binding; SNARE binding; SNAP receptor activity
Biological process: organelle membrane fusion; positive regulation of cell adhesion; positive regulation of cell population proliferation; positive regulation of chemotaxis; positive regulation of protein localization to cell surface; positive regulation of protein localization to plasma membrane; regulation of gene expression; exocytic insertion of neurotransmitter receptor to postsynaptic membrane; neuron projection development; intracellular protein transport; membrane fusion; modulation of chemical synaptic transmission; vesicle-mediated transport
Cellular component: apical plasma membrane; azurophil granule; cell-cell junction; extracellular exosome; lamellipodium; nucleus; plasma membrane; presynapse; specific granule; growth cone; neuron projection; photoreceptor inner segment; photoreceptor outer segment; postsynapse; SNARE complex; vacuole; cytoplasm; dendrite; glutamatergic synapse; melanosome; membrane; plasma membrane bounded cell projection; Schaffer collateral - CA1 synapse; secretory granule; zymogen granule membrane
Genetic constraint (gnomAD): Loss-of-function variants: 19 observed, 37.29 expected, observed/expected ratio (o/e) 0.51, 90% interval 0.35 to 0.75. The upper end of that interval is the gene's LOEUF score, 0.75, which puts it in group 3 of 6, group 1 being the genes least tolerant of losing a copy. Missense variants: 362 observed, 379.12 expected, observed/expected ratio (o/e) 0.95, 90% interval 0.88 to 1.04. Synonymous variants: 121 observed, 137.25 expected, observed/expected ratio (o/e) 0.88, 90% interval 0.76 to 1.02.
Homologues: Orthologues: macaque STX3 (99% identical), chimpanzee STX3 (97% identical), guinea pig STX3 (96% identical), rat Stx3 (92% identical), pig STX3 (88% identical), mouse Stx3 (88% identical), tropical clawed frog stx3 (80% identical), dog STX3 (76% identical), zebrafish stx3b (75% identical), zebrafish stx3a (64% identical), Caenorhabditis elegans unc-64 (56% identical), Drosophila melanogaster Syx1A (56% identical). Paralogues in human: STX2 (63% identical), STX1A (63% identical), STX1B (61% identical), STX4 (40% identical), STX11 (30% identical), STX19 (29% identical), STX5 (27% identical), STX12 (22% identical), STX7 (21% identical), STX16 (21% identical), STX17 (18% identical), TSNARE1 (15% identical).